PCSK9 (proprotein convertase subtilisin/kexin type 9)
Diseases named in the same sentence as PCSK9 in open-access papers (continued):
Sharing a sentence is not in itself a finding about the gene and the disease.
Ventricular arrhythmia (1 paper, 2025). "Third, PCSK9 inhibitors have been demonstrated to protect coronary artery endothelial function, which may decrease the probability of plaque rupture and prevent ischemia-induced electrophysiological disturbances that predispose patients to ventricular arrhythmias." (PMID 40779566, 2025). "PCSK9 inhibitors did not significantly reduce the risk of SCD or ventricular arrhythmias, though a non-significant trend suggested potential benefits for patients with ASCVD or higher cardiovascular risk." (PMID 40779566, 2025). "To address this gap, we conducted a systematic review and meta-analysis of large RCTs to assess whether PCSK9 inhibitor therapy can reduce the risk of SCD and ventricular arrhythmias." (PMID 40779566, 2025). "PCSK9 inhibitors have been shown to remarkably reduce cardiovascular events in patients at high risk, but data on their impact on sudden cardiac death (SCD) and ventricular arrhythmias are limited." (PMID 40779566, 2025). "In the primary analysis of 10 trials, PCSK9 inhibitors did not significantly reduce the risk of ventricular arrhythmias (RR 0.81, 95% CI 0.60–1.09; P = 0.17; I2 = 0%)." (PMID 40779566, 2025). "This study aimed to evaluate whether PCSK9 inhibitor therapy reduces the risk of SCD and ventricular arrhythmias." (PMID 40779566, 2025). "Therefore, PCSK9 inhibitor therapy may reduce the incidence of ventricular arrhythmias or SCD." (PMID 40779566, 2025). "However, reliable evidence from randomized controlled trials (RCTs) regarding the effects of PCSK9 inhibitors on SCD and ventricular arrhythmias remains limited." (PMID 40779566, 2025). "PCSK9 inhibitor therapy did not significantly reduce the risk of SCD and ventricular arrhythmias." (PMID 40779566, 2025). "PCSK9 inhibitor may exert beneficial effects on SCD and ventricular arrhythmias." (PMID 40779566, 2025).
cardiovascular disease (330 papers, 2011 to 2026). "Specifically, using CRISPR technology and lipid NPs, nearly complete hepatic suppression of the proprotein convertase subtilisin/kexin type 9 (PCSK9) gene—a factor increasing cardiovascular disease risk—was observed." (PMID 41294748, 2025). "People who lack functional PCSK9 as a result of such LOF mutations in the PCSK9 gene can lead normal lives, and these genetic variants protect them from developing cardiovascular diseases." (PMID 38886277, 2024). "Promising therapeutic drugs for the treatment of hypercholesterolemia and associated cardiovascular disorders are the inhibitors of PCSK9, namely evolocumab, alirocumab, inclisirian and bococizumab." (PMID 38509261, 2024). "PCSK9 antibodies have been identified as emerging agents that can reduce the risk of cardiovascular diseases, either as supplements to statins or as an alternative when statins are ineffective." (PMID 38887452, 2024). "PCSK9 inhibitors in combination with ezetimibe are recommended for patients with ASCVD or those at high risk for cardiovascular disease with plasma LDL-C levels above target in patients with statin intolerance [+, I, A]." (PMID 39697215, 2024). "In conclusion, PCSK9’s association with cardiovascular aging is a rapidly evolving area of research with significant implications for our understanding of age-related cardiovascular disease." (PMID 38105401, 2024). "Proprotein convertase subtilisin/kexin type 9 (PCSK9) inhibitors represent an effective strategy for reducing cardiovascular disease risk." (PMID 39010016, 2024). "Overall, these pivotal cardiovascular trials have illuminated the potential of PCSK9 inhibitors as effective tools in managing cardiovascular disease, particularly in high‐risk patient populations." (PMID 39479289, 2024). "PCSK9 inhibitors in combination with statins and ezetimibe are recommended for diabetic patients at high risk for cardiovascular disease who are on the maximum tolerated dose of statins and ezetimibe, with plasma LDL-C levels remaining above target [+, I, A]." (PMID 39697215, 2024). "PCSK9 is highly associated with cardiovascular disease, as the protein it encodes plays a key role in regulating blood cholesterol levels by controlling the number of low-density lipoprotein (LDL) receptors on the surface of liver cells." (PMID 37222281, 2023). "The overall goal was to deepen our current understanding of how nutrition or diet intake affects PCSK9 levels, impacting platelet activity and increasing the risk of cardiovascular diseases in an animal model." (PMID 37892538, 2023). "In the general population, serum PCSK9 concentration is associated with a future risk of cardiovascular disease, even after adjustments are made for established cardiovascular disease risk factors." (PMID 36768292, 2023). "Recently, the association between PCSK9 and extracellular vesicle-derived miRNA has been studied in the context of cardiovascular disease." (PMID 37860186, 2023). "ORION 9, 10, and 11 trials have proved inclisiran 284 mg has good tolerability and efficacy in long-term LDL-C reduction; PCSK9 plasma levels were reduced by about 80% in patients with a very high risk of cardiovascular disease." (PMID 36831039, 2023). "Inhibitors of proprotein convertase subtilisin-kexin type 9 (PCSK9) have demonstrated to lower the risk of cardiovascular disease, particularly in high-risk subjects such as those with T2DM." (PMID 36875491, 2023). "Caffeine inhibits the expression of SREBP2 at the transcriptional level by increasing the Ca2+ concentration in the hepatic ER, thereby reducing the expression of PCSK9 and the risk of cardiovascular disease." (PMID 36970356, 2023). "Accordingly, loss-of-function (LoF) variants are protective for cardiovascular disease, and less than 15 years after the discovery of this effect, therapeutic approaches to inhibit PCSK9 have been brought to market." (PMID 36778668, 2022).
cardiovascular disease (continued). "To test the in vivo therapeutic potential of the single-AAV ABE system, we installed in mice mutations that are associated with decreased cardiovascular disease risk in humans by precisely knocking down Pcsk9 or Angptl3 protein levels." (PMID 35902773, 2022). "In the ODYSSEY OUTCOMES trial, the reduction of Lp(a) levels by PCSK9 inhibitors was associated with a decrease in the risk of cardiovascular disease." (PMID 35548407, 2022). "As the interaction promotes elevated plasma LDL-C levels, and therefore a predisposition to cardiovascular disease, PCSK9 has attracted intense interest as a therapeutic target." (PMID 36209894, 2022). "After the report about its roles in cholesterol metabolism, extensive studies were conducted to elucidate the association between PCSK9 and cardiovascular disease, as well as their risk factors." (PMID 35207479, 2022). "PCSK9 deficiency significantly improves the survival rate of cardiovascular disease (CVDs) patients." (PMID 36381647, 2022). "Further studies in healthy subjects and cardiovascular disease patients are necessary to evaluate the role of HDL-associated PCSK9 forms in cardiovascular risk." (PMID 36067830, 2022). "Conversely, changes of HDL-C [MD = 6.27, CI (5.17 to 7.36), P < 0.00001] and ApoA1 [MD = 4.33, 95% CI (3.53 to 5.13), P < 0.00001] from baseline were significantly more in high cardiovascular disease risk patients who received PCSK9 inhibitors treatment." (PMID 35529059, 2022). "Improvements for medical therapy are obtained from established studies that successfully provide new information on the causes of cardiovascular disease, one of which is the PCSK9 study on platelet activation." (PMID 36005422, 2022). "Within this setting PCSK9 inhibitors were mainly prescribed in secondary prevention for patients with established cardiovascular disease and multiple cardiovascular risk factors." (PMID 33894772, 2021). "In this context, major efforts over the last years have resulted in the clinical application of anti-PCSK9 antibodies to reduce circulating lipid levels and thereby the risk for cardiovascular disease." (PMID 34884827, 2021). "Protease proprotein convertase subtilisin/kexin type 9 (PCSK9), a risk factor of cardiovascular diseases, is negatively associated with memory function in elderly females but not in males." (PMID 34220488, 2021). "In patients with high cholesterol and at risk of cardiovascular disease, inhibitors of PCSK9 are useful in lowering lipid levels but must be dosed regularly." (PMID 35602209, 2021). "Monoclonal antibodies target to PCSK9 are relatively novel lipid-lowering agents that have benefits in reducing the risk of cardiovascular disease." (PMID 34887772, 2021). "Many studies have indicated that circulating PCSK9 levels are positively associated with cardiovascular disease and the risk of total cardiovascular (CV) events." (PMID 34075144, 2021). "Although the introduction of lipid-lowering therapies, such as 3-hydroxy-3-methylglutaryl coenzyme A reductase (HMGCR) inhibitors and proprotein convertase subtilisin-kexin type 9 (PCSK9) inhibitors have lowered the risk of cardiovascular disease." (PMID 33381046, 2020). "We describe a patient with heterozygous FH treated with PCSK9 inhibitor over the course of two years, and the drug's impact on carotid intima-media thickness, Achilles tendon thickness, and cardiovascular disease risk reduction." (PMID 33094041, 2020). "The reduced number of cardiovascular diseases in patients diagnosed with PCSK9 LOF mutations justifies the development of PCSK9 suppressors." (PMID 33062601, 2020).
cardiovascular disease (continued). "Cardiovascular disease is expected to remain the leading cause of death worldwide despite the introduction of proprotein convertase subtilisin/kexin type 9 inhibitors that effectively control cholesterol." (PMID 30675518, 2019). "Although PCSK9 inhibitors were shown to reduce the risk of cardiovascular disease, a warning was issued concerning their possible impact on cognitive functions." (PMID 31437157, 2019). "Subsequently, loss-of-function PCSK9 variants were associated with decreased plasma cholesterol and lowered lifetime incidence of cardiovascular disease." (PMID 30251625, 2018). "PCSK9 is a secreted protein that regulates plasma cholesterol levels and cardiovascular disease risk." (PMID 30251625, 2018). "Based on their efficacy and safety, the U.S. Food and Drug Administration (FDA) recently approved evolocumab and alirocumab, two PCSK9 inhibitor drugs, for use in select individuals at high risk for cardiovascular disease (CVD)." (PMID 28081164, 2017). "Four case-control studies and three cohort studies revealed the association between PCSK9 rs11591147 polymorphism and cardiovascular disease risk, a total of 60,677 subjects included in this group and all of them were Caucasians." (PMID 28606094, 2017). "Plasma PCSK9 levels have been reported to be associated with severity of CAD as well as future risk of cardiovascular disease." (PMID 27658826, 2016). "Over the last decade, inhibition of proprotein convertase subtilisin/kexin type 9 (PCSK9) has emerged as a promising therapeutic strategy to reduce residual cardiovascular disease risk." (PMID 27095708, 2016). "To address this gap, we examined the association of common and rare variants in PCSK9 and blood pressure in a population of African Americans at high risk for cardiovascular disease." (PMID 25904937, 2015). "The goal of this study was to examine if common and rare polymorphisms in PCSK9 are associated with blood pressure in an African-American population at high risk for cardiovascular disease." (PMID 25904937, 2015). "The proprotein convertase subtilisin/kexin type 9 (PCSK9) has emerged as a promising treatment target to lower serum cholesterol, a major risk factor of cardiovascular diseases." (PMID 25600226, 2015). "MR methods have been used previously to investigate the role of high-density lipoprotein and C-reactive protein in predisposition to cardiovascular disease, and have provided strong evidence that PCSK9 inhibition prevents cardiovascular disease." (PMID 26305103, 2015). "Reduction of circulating PCSK9 levels or activity is presently an attractive approach to lower LDLc and associated risk of developing cardiovascular disease." (PMID 23675525, 2013). "Among the proteins with a proven role in the development of cardiovascular diseases, my study focused on proprotein convertase subtilisin/kexin type 9 (PCSK9), investigating the causes of the changes in total cholesterol and its fractions in the male subjects identified in the previous study." (PMID 40136460, 2025). "Hence, the intervention of PCSK9 have been identified as novel therapeutic strategies to potentially attenuate the risk of cardiovascular diseases." (PMID 39404968, 2024). "PCSK9, the attractive molecular target for controlling and decreasing the risk of cardiovascular diseases, is involved in the evolution of atherosclerotic plaques, while the PCSK9 inhibitor (i-PCSK9), evolocumab, displays beneficial effects in vascular function." (PMID 37587410, 2023).
cardiovascular disease (continued). "Despite mounting evidence that PCSK9 inhibitors can lower cholesterol levels and reduce the risk of cardiovascular disease, the basic processes underpinning PCSK9 inhibitors' effects on cardiac function have not been studied enough and it requires further research." (PMID 36895542, 2023). "Together, the data presented in this study suggest that in addition to its anti-obesogenic and anti-steatotic effect, ME significantly improves serum lipid profile and reduces levels of pro-atherogenic PCSK9, which likely attenuates the risk of cardiovascular disease." (PMID 37242292, 2023). "Thus, PCSK9 inhibitors reduce cardiovascular disease risk alone and in combination with statins despite some cases in actual clinical situations where lowering the LDL-C below the goal is difficult due to the adverse effects of statins or other causes." (PMID 37109734, 2023). "PCSK9 inhibitors have an additional benefit when compared to statin therapy, in which they decrease lipoprotein a (Lp(a)) concentrations that are directly associated with a higher risk of cardiovascular diseases." (PMID 36935878, 2023). "In addition, the loss of function of the PCSK9 gene has been considered protective against cardiovascular disease, while the gain of functional mutation of PCSK9 exacerbates cardiovascular risks." (PMID 34996457, 2022). "Disabling the PCSK9 gene using gene editing technologies may allow a one-shot injection as a preventative treatment to reduce the risk of cardiovascular disease, however, the safety of such treatments are still being extensively evaluated." (PMID 34731223, 2021). "Therefore, PCSK9 plays a vital role in the pathogenesis of cardiovascular disease and cancer, the top two causes of morbidity and mortality worldwide." (PMID 34782856, 2021). "Novel and costly therapies are available, such as PCSK9 inhibitors, and new antithrombotic treatment schemes, such as dual antiplatelet therapy or adding rivaroxaban to aspirin (dual pathway inhibition), aiming to reduce cardiovascular disease risk." (PMID 33580447, 2021). "We propose that new therapies that are more effective in lowering phytosterols, particularly in depleting stigmasterol from the body, represent a valuable therapeutic strategy for reducing residual risk of cardiovascular disease in the post-PCSK9 inhibitor era of tightly controlled cholesterol." (PMID 30675518, 2019). "Therefore, considering the lipid-lowering effects and the incidence of cardiovascular events, PCSK9 inhibitors may become the preferred treatment option for patients at high risk of cardiovascular disease." (PMID 41478627, 2025). "This raises the question, whether the atherosclerotic process accelerates in RA patients as a result of longer exposure to chronic systemic inflammation, or if RA treatments impact PCSK9 levels and, consequently, lead to an increased risk of cardiovascular disease." (PMID 40480650, 2025). "These conditions may promote enhanced activation of sterol regulatory element-binding protein 2 (SREBP2) and hepatocyte nuclear factor-1 alpha (HNF1α) dependent transcription of PCSK9, thereby linking tobacco exposure to impaired lipid metabolism and increased cardiovascular disease risk." (PMID 41516208, 2025). "Proprotein convertase subtilisin/kexin type 9 inhibitors (PCSK9i) reduce cholesterol levels and cardiovascular disease risk, particularly in patients with SR-FH, where PCSK9i may differentially affect pro- and anti-inflammatory mediators depending on the clinical setting." (PMID 39091354, 2024). "However, there are several other associations between PCSK9 and cardiovascular diseases." (PMID 36900189, 2023). "Several studies have shown the positive association between PCSK9 and triglycerides levels, and PCSK9 inhibition has been demonstrated to influence triglyceride-rich lipoprotein metabolism which is also a risk factor for cardiovascular disease and vascular inflammation." (PMID 35596184, 2022).